ENSG00000288710 (novel protein)
Gene: Protein-coding gene on chromosome 12 (49,002,274 to 49,024,075, reverse strand). Ensembl gene ENSG00000288710.
Genetic constraint (gnomAD): Missense variants: 77 observed, 260.28 expected, observed/expected ratio (o/e) 0.3, 90% interval 0.25 to 0.36. Synonymous variants: 95 observed, 97.34 expected, observed/expected ratio (o/e) 0.98, 90% interval 0.83 to 1.16.